TATDN1 (TatD DNase domain containing 1)
Description:
Exhibits 3'-5' exonuclease and apurinic/apyrimidinic (AP) endonuclease activities (in vitro). Shows preferential AP endonuclease activity on dsDNA substrates and 3'-5' exonuclease activity on ssDNA. Catalyzes decatenation of catenated kinetoplast DNA to produce separated linear DNA in vitro (By similarity). Plays an important role in chromosomal segregation and cell cycle progression during eye development probably via its DNA decatenation activity (By similarity).
Synonyms: CDA11
Tractability: Small molecule: a structure with a bound ligand is known; it has a binding pocket of medium quality. PROTAC: ubiquitination databases record sites on it; its protein half-life has been measured.
Gene: Protein-coding gene on chromosome 8 (124,488,485 to 124,539,458, reverse strand). Ensembl gene ENSG00000147687.
Subcellular location: Nucleus
Subcellular location (Human Protein Atlas): Nucleoplasm
Gene Ontology:
Molecular function: 3'-5'-DNA exonuclease activity; DNA endonuclease activity; protein binding; hydrolase activity, acting on ester bonds
Cellular component: mitochondrion; nucleoplasm; nucleus
Genetic constraint (gnomAD): Loss-of-function variants: 21 observed, 24.04 expected, observed/expected ratio (o/e) 0.87, 90% interval 0.62 to 1.26. The upper end of that interval is the gene's LOEUF score, 1.26, which puts it in group 5 of 6, group 1 being the genes least tolerant of losing a copy. Missense variants: 173 observed, 181.11 expected, observed/expected ratio (o/e) 0.96, 90% interval 0.84 to 1.08. Synonymous variants: 58 observed, 50.83 expected, observed/expected ratio (o/e) 1.14, 90% interval 0.92 to 1.42.
Homologues: Orthologues: chimpanzee TATDN1 (99% identical), macaque TATDN1 (97% identical), pig TATDN1 (95% identical), guinea pig TATDN1 (94% identical), rabbit TATDN1 (94% identical), rat Tatdn1 (92% identical), mouse Tatdn1 (90% identical), dog TATDN1 (86% identical), tropical clawed frog tatdn1 (70% identical), Drosophila melanogaster CG3358 (45% identical), zebrafish tatdn1 (44% identical). Paralogues in human: TATDN2 (24% identical), TATDN3 (20% identical).
Diseases named in the same sentence as TATDN1 in open-access papers:
TATDN1 is named in the same sentence as 9 diseases in open-access papers, as found by Europe PMC text mining. Sharing a sentence is not in itself a finding about the gene and the disease. The quoted sentences say what the papers report.
breast carcinoma (3 papers, 2024 to 2025). "For example, for fusion TATDN1::GSDMB in breast cancer cell line SKBR3, we find evidence of 13 distinct fusion transcript isoforms." (PMID 38464114, 2024).
lung carcinoma (3 papers, 2016 to 2024). "Our findings have shown the potential of TATDN1 in regulating lung cancer metastasis, and that the Wnt/β-catenin signal pathways and PI3K/AKT/MTOR pathway may be involved in the key mechanism of its anti-metastatic effect." (PMID 26943769, 2016). "Overexpression of metastasis-associated lung adenocarcinoma transcript 1 (MALAT1), SBF2 antisense RNA 1 (SBF2-AS1), and Homo sapiens TatD DNase domain containing 1 (TATDN1) is capable of enhancing the ability of proliferation, metastasis, and invasion of lung cancer." (PMID 27589728, 2016).
hepatocellular carcinoma (2 papers, 2022 to 2024). A malignant tumor that arises from hepatocytes. "As a highly conserved nuclease, TatD DNase domain containing 1 (TATDN1), a member of the TATD family, has been found upregulated in hepatocellular carcinoma (HCC) and cisplatin-resistant NSCLC." (PMID 35923577, 2022).
dilated cardiomyopathy (1 paper, 2025). Cardiomyopathy which is characterized by dilation and contractile dysfunction of the left and right ventricles. "Tatdn1-deficient mice exhibit dysregulated expression of genes involved in membrane and extracellular protein biology, along with mild dilated cardiomyopathy and impaired motor coordination." (PMID 40123200, 2025).
cancer (2 papers, 2023 to 2025). A tumor composed of atypical neoplastic, often pleomorphic cells that invade other tissues. "Despite its association with different pathologies, including several cancer types and cardiovascular diseases, the role of TATDN1 in mammals remains unexplored." (PMID 40123200, 2025). "Several studies have reported that TATDN1 overexpression in cancers is associated with poor prognosis." (PMID 36881763, 2023).
tumor (2 papers, 2016). "Moreover, knockdown TATDN1 also inhibited tumor growth and metastasis in a 95D mouse model in vivo by inhibiting β-catenin and Ezrin." (PMID 26943769, 2016). "We found that TATDN1 (Homo sapiens TatD DNase domain containing 1, TATDN1), one of LncRNAs, was highly expressed in 95D cells and NSCLC tumor tissues compared to 95C cells." (PMID 26943769, 2016).
hematological malignancies (1 paper, 2011). "ACACA, RARA, NOTCH1 and NUP214 are known to form translocations in various types of hematological malignancies while many other fusion genes involve suspected oncogenes, such as RPS6KB1 (RPS6KB1-TMEM49 and RPS6KB1-SNF8), GSDMB (TATDN1-GSDMB) and MCF2L (LAMP1-MCF2L)." (PMID 21247443, 2011).
TATDN1 also shares sentences with these, for which no sentence is quoted: cardiovascular diseases (1 paper); non-small cell lung carcinoma (1).